AFP (alpha fetoprotein)
Diseases named in the same sentence as AFP in open-access papers (continued):
Sharing a sentence is not in itself a finding about the gene and the disease.
tumor (continued). "Similarly, combining AFP with inflammatory markers like C-reactive protein or IL-6 may improve prognostic stratification by reflecting both tumor burden and systemic inflammation, which are critical drivers of HCC progression." (PMID 40221793, 2025). "The absence of a significant association between changes in AFP levels and tumor recurrence may be explained by the temporal gap between follow-up sample collection and the actual onset of recurrence." (PMID 41002319, 2025). "In addition, the PBIShi group showed higher AFP levels, intrahepatic tumor size, and a higher percentage of multiple tumors, suggesting that the PBIShi group may have a higher tumor burden than that in the PBISlo group." (PMID 40568585, 2025). "Furthermore, a strong association between elevated PTX3 expression and higher serum alpha fetoprotein (AFP) levels, larger tumor size, and more advanced tumor stages suggests that PTX3 could serve as a prognostic biomarker for HCC." (PMID 41479916, 2025). "While current tissue-based approaches (including our DIA proteomics) may not fully resolve intratumoral heterogeneity compared to advanced spatial techniques like laser-capture microdissection, this model overcomes AFP’s critical limitation in capturing tumour microenvironment architecture." (PMID 40673276, 2025). "First, methodologies for the detection of serum tumor markers (AFP, AFP-L3% and PIVKA-II) and laboratory tests (TBIL, ALB and PLT) vary by clinical settings, so the observed efficacy of serum tumor markers and diagnostic models may be different from those in this study." (PMID 40708828, 2025). "Additionally, increased AFP production may reflect hepatic differentiation presence in tumor cells, potentially enhancing their metastatic potential." (PMID 40485723, 2025). "This observed discrepancy in AFP level trends may reflect a difference in the tumor biology of HCC between the two datasets, potentially leading to an unexpectedly reduced diagnostic yield in the external validation dataset when utilizing a model incorporating AFP as a feature." (PMID 40231168, 2025). "Co-expression of β-hCG and AFP may indicate a more aggressive tumor phenotype and poorer prognosis." (PMID 41552242, 2025). "However, the potential correlation between AFP and the number of tumor cells is often overlooked." (PMID 40857604, 2025). "In addition, discrepancies between AFP levels and tumor size or stage may occur, requiring cautious interpretation when using AFP for staging or prognostic evaluation." (PMID 40430002, 2025). "In contrast, sustained elevation during follow-up, particularly in the absence of infection or other inflammatory conditions, may suggest residual disease or early recurrence prior to the detectable rise in traditional serum tumor markers such as alpha-fetoprotein or human chorionic gonadotropin." (PMID 41283275, 2025). "Notably, patients with fatal outcomes and more aggressive tumor characteristics—including higher histological grade, markedly elevated AFP levels, presence of vascular invasion, and more advanced TNM staging—demonstrated significantly elevated LRRPS values in the TCGA cohort." (PMID 40269756, 2025). "Additionally, HCC tumor-derived alpha-fetoprotein (AFP) has been shown to disrupt DC metabolism by inhibiting mTORC1 signaling, resulting in defective oxidative phosphorylation, impaired mitochondrial integrity, and a diminished capacity to stimulate T cells in vitro." (PMID 40721870, 2025). "Notably, preclinical studies have shown that AFP vaccination can activate antigen-specific T cell responses and enhance anti-tumor immunity, providing a rationale for exploring combination strategies with immune checkpoint inhibitors in AFP-positive HCC patients." (PMID 41403946, 2025).
tumor (continued). "The recently proposed SMARS score (acronym comprising Shape of tumour, Mosaic architecture, AFP level, Rim APHE, and Satellite lesion) could discriminate proliferative and non-proliferative HCC tumours in a non-invasive way and was associated with treatment outcomes." (PMID 40640280, 2025). "Herein, demographic information, as well as tumor (diameter, differentiation grade), inflammatory, and hepatic function parameters were examined, revealing statistically significant intergroup differences in tumor diameter, AFP, GGT, and differentiation grade (P < 0.05)." (PMID 41237121, 2025). "Furthermore, dynamic changes in tumor markers, such as AFP and PIVKA-II, during treatment may reflect tumor response more sensitively than static baseline values." (PMID 41008900, 2025). "Additionally, reductions in tumor markers such as alpha-fetoprotein (AFP) were also observed." (PMID 40432108, 2025). "Regarding biomarkers, GCTs may secrete specific circulating tumour markers, including AFP and HCG." (PMID 41523526, 2025). "Additionally, AFP may alter the tumor microenvironment by promoting chronic inflammation and recruitment of immunosuppressive cells, creating a more favorable environment for tumor cells to evade the effects of therapies." (PMID 40430002, 2025). "Additionally, we identified two critical thresholds: 60% tumor size reduction and 25% AFP decline." (PMID 40934000, 2025). "High clinical suspicion, determination of serum markers (AFP and β-hCG) and histologic confirmation should guide the management of patients with mediastinal, retroperitoneal, and midline CNS tumors, in the setting of multidisciplinary tumor boards, to identify a subset of highly curable patients." (PMID 40304839, 2025). "Notably, early recurrence within 2 years after surgery has been confirmed as an independent risk factor for treatment failure and poor prognosis, which may be related to alpha-fetoprotein (AFP), tumor size, and microvascular invasion (MVI)." (PMID 40165325, 2025). "Elevated levels of tumor markers were observed, with carcinoembryonic antigen levels of 8.4 ng/dL (normal < 5.0 ng/dL), protein induced by vitamin K absence or antagonist‐II levels of 28 413 mAU/mL (normal < 40 mAU/mL), and AFP levels of 24 502 ng/mL (normal < 10 ng/mL)." (PMID 40922714, 2025). "In addition, tumor number, microvascular invasion, thickness of resection margin, AFP, AST and GGT were the independent risk factors of DFS, while PS score, tumor number, maximal tumor size, ES classification, microvascular invasion, AST and GGT were the independent risk factors of OS." (PMID 41180318, 2025). "Tumour markers (TMs) aid the diagnosis, prognostication, monitoring of chemotherapy, and long-term surveillance of patients with GCTs, and elevations of α-fetoprotein (AFP) and human chorionic gonadotrophin (hCG) have good positive predictive value for GCT in the context of a testicular lump." (PMID 39934683, 2025). "Prior research has shown that high AFP levels may indicate tumor progression." (PMID 39714631, 2025). "In addition to these roles, dynamic changes in AFP levels, commonly referred to as AFP response, have been validated as effective in monitoring the efficacy of anti-tumor treatments, where decreases post-treatment suggest an encouraging overall therapeutic response." (PMID 38433845, 2024). "Similarly, AFP >400 ng/ml [P = 0.012, HR = 2.125 (1.874–4.356)], incomplete tumor capsule [P = 0.032, HR = 3.387 (1.811–4.474)] and I-O and MTT [P = 0.037, HR = 0.851 (0.622–0.914)] were independent prognostic factors of overall survival after hepatectomy for HCC with PVTT." (PMID 39170098, 2024). "Furthermore, tumor markers (AFP and CA-199) were maintained at low levels during treatment." (PMID 39195212, 2024).
tumor (continued). "In addition, patients with HCC were categorized into different groups based on their age, gender, AFP level, tumor grade, TNM stage, and vascular invasion to verify whether our predictive model could be an effective supplement to the current staging system." (PMID 39434887, 2024). "Moreover, a significant elevation of AFP levels above 1000 mcg/L has been associated with an increased risk of recurrence in transplanted patients, regardless of tumor size." (PMID 38396674, 2024). "In addition, higher AFP level, poor differentiation grade, recurrent tumor and treatment type were independent prognostic factors for OS, while poor differentiation grade, larger tumor size and treatment type were the independent prognostic factors for DSS (all P < 0.05)." (PMID 39354331, 2024). "Notably, tumor size exerted a greater influence on PIVKA-II and AFP levels than tumor number, type, or metastasis, suggesting that patients with positive AFP and PIVKA-II may have a poorer prognosis." (PMID 39432605, 2024). "However, we found that only a small subset of adult PB cases exhibit elevated tumor markers, including AFP and CA19‐9, which may be instructive, and vigilance is still needed when the condition is clinically present." (PMID 39162366, 2024). "Despite the current data available, a consensus on the optimal pre-transplant AFP level to predict post-transplant survival is yet to be determined, and many proposed scores for transplant candidacy have proposed different AFP cutoffs based on tumor size and number." (PMID 38672535, 2024). "Moreover, the sensitivity of AFP is subject to various factors, including tumor size." (PMID 39200161, 2024). "Additionally, the staining intensity of FAP and DAB2 also exhibited a significant positive correlation with tumor size and patient serum AFP concentration (Spearman correlation analysis, P < 0.0001), suggesting their potential as indicators of tumor progression in clinical practice." (PMID 39239526, 2024). "Recurrence after LT can be estimated by the Risk Estimation of Tumour Recurrence After Transplant (RETREAT) score, which holds significant value in guiding post-LT surveillance and treatment by utilising pre-transplant alpha-fetoprotein (AFP) levels and pathological explant data." (PMID 38920705, 2024). "However, the relationship between tumor markers, such as AFP and DCP, and the radiological OR in such patients remains unclear." (PMID 39321197, 2024). "Here, the AFP rise may have represented more sustained ongoing tumor kill from weekly chemotherapy, in a tumor type which is generally less exquisitely chemosensitive compared with GCTs, and which therefore typically requires longer treatment courses than those used for cure for patients with GCTs." (PMID 38098239, 2024). "Therefore, supplementing the IL-21 signal to AFP-TCR-T may support its antitumor function within the HCC tumor microenvironment, which is deprived of the IL-21 signal." (PMID 38643203, 2024). "Additionally, our results suggest that integrating AFP response with preoperative radiological tumor response could offer potential advantages for prognostic evaluation." (PMID 38433845, 2024). "Simultaneously, AFP may also suppress the function of NK cells, macrophages, DCs, CAFs, endothelial cells, and mesenchymal stem cells, and impair the ability of cytotoxic T lymphocytes to eliminate tumor cells, thus facilitating tumor immune evasion." (PMID 38660138, 2024). "Also, HCC tumor samples with higher PRMT3 expression had clinicopathologic features associated with more aggressive disease, such as larger tumor sizes, advanced tumor stages, and higher AFP levels." (PMID 39256398, 2024). "Increased production of hormones physiologic for adult animals (e.g., adrenocorticotropin, norepinephrine, and erythropoietin) or typical for the foetal phase (alpha‐fetoprotein, anti‐Müllerian hormone, and parathyroid‐hormone‐related protein) might aid in tumour diagnostics." (PMID 36495211, 2023).
tumor (continued). "In addition to certain biomarkers, clinicopathological variables are easily accessible and have been widely applied to predict postoperative recurrence and clinical outcomes in HCC patients, including serum AFP level, tumor size, tumor number and the presence of MVI." (PMID 37370037, 2023). "More patients treated with HAIC had BCLC stages A and B. AFP levels and tumor size were significantly higher in patients treated with HAIC than in those treated with AB, which may be because several terminal patients were palliatively treated with HAIC despite worse liver function." (PMID 37686509, 2023). "Furthermore, monitoring PIVKA-II levels in HCC transplant recipients reflects the tumor early recurrence after transplantation and could be used, complementing AFP and imaging tests, as a novel biomarker of this pathology." (PMID 37024609, 2023). "Moreover, AFP is a well-known tumor marker for both HCC diagnosis and prognosis." (PMID 37200967, 2023). "Furthermore, AFP, albumin and tumor burden were combined to identify the patients who may benefit from liver resection and may be moved forward to BCLC stage A from advanced-HCC patients with PS1 alone." (PMID 37434986, 2023). "Our results also suggested that patients with certain characteristics (low grade, M0, radiotherapy received, chemotherapy received, negative AFP, and small tumor size), namely the patients with low risk, may have good survival when receiving surgery." (PMID 37576968, 2023). "In addition, a study found that hepatic arterial infusion of artesunate was similar to conventional Transcatheter arterial chemoembolization (TACE) therapy in reducing tumor size, reducing the short-term efficacy of AFP, and reducing interventional side effects." (PMID 38072951, 2023). "However, AFP is valuable as an early marker for assessing the completeness of tumor resection as well as for monitoring malignant recurrence after initial surgery (75% of recurrences show elevated AFP) and chemotherapy (monitoring for up to 3–5 years post-treatment)." (PMID 37686577, 2023). "Also, tumor markers (AFP, GPC3, and VEGF) were significantly enhanced in the HCC group." (PMID 37759583, 2023). "Post‐operative presence of identified tumor mutations showed significant correlation with patients' relapse free survival, providing a potent tool for MRD detection, which could be further combined with AFP for more accurate evaluation." (PMID 37496285, 2023). "Median tumor marker levels were different pre‐orchiectomy compared to pre‐chemotherapy, although this did not result in a change in risk category in most cases: AFP 28 versus 13 μg/L (IQR 186 μg/L), hCG 25 versus 9 U/L (IQR 435 U/L), and LDH 277 versus 244 U/L (IQR 185 U/L)." (PMID 37392170, 2023). "Based on previous findings, we wonder whether AFP is involved in regulating tumor immune evasion." (PMID 37336873, 2023). "Although elevation of β-human chorionic gonadotropin (β-HCG) and α-fetoprotein (AFP) levels suggested that a large pineal mass lesion observed on magnetic resonance imaging (MRI) might be a β-HCG/AFP-producing tumor, whether the mass was truly a GCT remained unclear." (PMID 38066820, 2023). "Therefore, it may add valuable information to other preoperative findings, such as tumor size, tumor number and AFP level." (PMID 35451699, 2023). "In addition to the serum AFP level, the tumor size is also an indicator of prognosis." (PMID 36902673, 2023). "AFP, as the most widely applied serum biomarker applied in HCC patient management, does not meet the clinical requirements, as demonstrated by its low sensitivity (only approximately 30%) in predicting tumor relapse and its weak associations with patient survival." (PMID 37337648, 2023).
tumor (continued). "Similarly, univariable logistic regression analysis revealed that the presence of MiVI was related to tumor size ≥5 cm and the presence of SN and AFP ≥400 ng/ml, while multivariate logistic regression analysis only identified AFP ≥400 ng/ml as an independent risk factor for MiVI." (PMID 36354141, 2023). "Similarly, this correlation with AFP level and tumor diameter was observed for TERT C228T VAF." (PMID 37298294, 2023). "This neoplasm may produce AFP and/or β-hCG, which can assist diagnosis and treatment monitoring." (PMID 37508611, 2023). "We hypothesized that the AFP response to LRT might predict tumor recurrence after LDLT." (PMID 36900345, 2023). "Thus, we could roughly predict the MVI status through the diameter of the tumor, the level of serum AFP and the number of tumors." (PMID 37118720, 2023). "The tumor is composed of Sertoli cells, Leydig cells, fibroblasts, and stromal cells in varying proportions, but may also have a component of glandular intestinal cells producing mature or immature hepatocytes, which are responsible for AFP production." (PMID 37686577, 2023). "Similarly, thioacetamide-induced HCC rats treated with adiponectin presented an 80% increase in survival rate, a 73% reduction in average number of liver nodules, 46% decrease in serum alpha-fetoprotein (AFP), as well as a reduced expression of tumor invasion markers, TNF-α and NF-κΒ." (PMID 37958479, 2023). "AFP mRNA is a possible marker only present in hepatic cells and could indicate tumor proliferation." (PMID 37509493, 2023). "However, several selection criteria, i.e., the Milan and UCSF criteria, limit the number of tumor nodules to a maximum of 3, while others, i.e., the alpha-fetoprotein (AFP), Metroticket 2.0, and Up-to-7 models, include HCC patients with more than 3 tumor nodules." (PMID 36967432, 2023). "Accordingly, with NICE guidelines, we think that patient age, site of metastases, and serum tumor markers such as alpha-fetoprotein, human chorion gonadotropin, and lactate dehydrogenase may be more effective in the diagnosis of germ cell origin than tissue immunophenotyping." (PMID 36346458, 2023). "We recorded sex, age, operation mode, smoking and drinking habits, BMI, serum AFP level, whether they were infected with hepatitis B virus, tumor number, maximum tumor diameter, histological grading, microvascular invasion risk grading, Child-Pugh grading, and CNLC staging." (PMID 38074100, 2023). "In addition to that, there are many predictors of recurrence other than the type of the graft such as level of AFP, vascular invasion and tumor grade that could be used to fairly allocate graft to those with lower incidence of recurrence." (PMID 36564609, 2023). "Moreover, MG(18:2/0:0/0:0) was the only prognostic biomarker among 15 metabolites, which is significantly associated with tumor-free survival of AFP negative HCC patients (HR=1.160, 95%CI 1.012-1.330, P=0.033)." (PMID 36845695, 2023). "We repeated expression-profiling patterns for key CmPn players, along with AFP, in liver tumor tissues using patient clinical data including race, family cancer history, and vascular invasion, as well as follow-up data regarding new tumor events/sites and vital status." (PMID 36980321, 2023). "Additionally, CDCA8 overexpression was positively correlated with AFP levels, increased tumor numbers, vascular invasion, and shorter survival, indicating that CDCA8 is involved in the malignant behavior of HCC and is correlated with worse outcomes for HCC patients." (PMID 36639822, 2023). "Also, only a small proportion of tumours at an early stage (10-20%) present with elevated AFP." (PMID 37432493, 2023). "The median AFP changed from 88 ng/mL (quartiles 6–1033) to 7 ng/mL (quartiles 5–12), the median number of tumors changed from four (quartiles 3–5) to one (quartiles 1–2), and the median maximum tumor diameter changed from 47 mm (quartiles 31–65) to 25 mm (quartiles 14–35)." (PMID 37958395, 2023).